GDF15 (growth differentiation factor 15)
Diseases named in the same sentence as GDF15 in open-access papers (continued):
Sharing a sentence is not in itself a finding about the gene and the disease.
hemorrhagic stroke (2 papers, 2021 to 2023). A stroke caused by a bleed on the brain. "Further studies evaluating the potential utility of adding GDF-15 for clinical prediction of hemorrhagic stroke risk in certain situations would be of great interest." (PMID 34177769, 2021). "However, this is the first study to specifically show associations of GDF-15 levels with spontaneous incident hemorrhagic strokes in the general population." (PMID 34177769, 2021). "The specific association between GDF-15 and incident hemorrhagic stroke has not previously been studied in the general population, to our knowledge." (PMID 34177769, 2021). "However, the association between GDF-15 and incidence of hemorrhagic strokes has not, to our knowledge, been specifically investigated." (PMID 34177769, 2021). "We hypothesized that there may be an association of GDF-15 with incidence of hemorrhagic strokes in the general population, which has not been investigated before." (PMID 34177769, 2021). "Higher circulating concentrations of GDF-15 were associated with both incident ICH and incident SAH in a nested case–control study, but samples were not collected after hemorrhagic stroke." (PMID 37446186, 2023).
Hepatitis (2 papers, 2022 to 2024). Inflammation of the liver. "Our findings suggest that, in patients with AIH, GDF15 is produced at the site of hepatitis, and serum GDF15 levels are elevated." (PMID 35610317, 2022). "Further investigation of atypical AIH, such as acute onset AIH and drug-related AIH, is important and should clarify whether GDF15 can distinguish atypical AIH from acute hepatitis and drug-induced hepatitis." (PMID 35610317, 2022).
hepatitis B (2 papers, 2011 to 2025). "Similarly, ROC analysis showed that GDF-15 values had excellent statistically significant diagnostic value in predicting hepatitis B (p < 0.001, AUC = 0.920)." (PMID 41157623, 2025). "We investigated the diagnostic properties of quantitative values of the biomarkers CCL-20, CXCL-16, CD8a, and GDF-15 in predicting hepatitis B using ROC curve analysis." (PMID 41157623, 2025).
hepatopathy (2 papers, 2018 to 2022). "Of course, decreased lipid fractions could also occur in the setting of liver dysfunction associated with severe HF, an aspect that would also explain the linear increases of GDF-15 in acute HF, and its direct correlations with the markers of liver injury." (PMID 36556311, 2022).
Hypoalbuminemia (2 papers, 2021 to 2022). The concentration of albumin in the blood circulation is below the lower limit of normal. "The results above support our findings that higher GDF15 levels were associated older age, longer HD duration, hypoalbuminemia, and higher risks in the fatal events." (PMID 33670413, 2021). "Accordingly, older age, higher GDF15, and hypoalbuminemia were integrated as a novel death risk score system in our modified prediction model." (PMID 33670413, 2021). "Age, GDF15, and hypoalbuminemia predict all-cause and CV death in MHD patients, yet a combination scoring system provides more robust predictive powers." (PMID 33670413, 2021). "As a result, age > 65 years old (score 1), GDF15 tertiles 1–3 (score 1–3) and hypoalbuminemia < 3.8 g/dL (score 1) were combined as a death score system in the secondary analyses." (PMID 33670413, 2021). "In the secondary analyses, age, biomarker GDF15, and hypoalbuminemia were incorporated into a novel GDF15-baesd death prediction model for the ROC analysis." (PMID 33670413, 2021). "In addition, the predictive value of the GDF-15/albumin ratio was better than that of GDF-15 alone or other markers such as overhydration status or hypoalbuminemia proven by ROC analysis." (PMID 35204349, 2022).
Hypoglycemia (2 papers, 2022 to 2025). A decreased concentration of glucose in the blood. "Probably because of the reduced sympathetic response, blood glucose levels 120 and 180 min after insulin injection in Gdf15-KO mice were significantly lower than those in control mice, suggesting an impaired response to hypoglycemia." (PMID 41034527, 2025).
hypothyroidism (2 papers, 2017 to 2025). Abnormally low levels of thyroid hormone. "Further studies will need to explore whether higher GDF15 levels could have a role in the increased cardiovascular risk found in patients with hypothyroidism." (PMID 41303556, 2025).
infiltrating ductal carcinomas (2 papers, 2019 to 2022). "We also analyzed the Oncomine database and found the expression level of GDF15 transcript was significantly higher in invasive ductal breast carcinoma tissues than that in normal breast tissues." (PMID 31861872, 2019).
insomnia (2 papers, 2020 to 2023). A sleep disorder characterized by difficulty in falling asleep and/or remaining asleep. "We have measured for the first time three of the most studied mitokines (FGF21, GDF15 and HN) in the framework of insomnia." (PMID 32420904, 2020).
ischemic cardiomyopathy (2 papers, 2021 to 2026). Ischemic cardiomyopathy is a cardiomyopathy in which a weakness in the muscle of the heart due to inadequate oxygen delivery to the myocardium with coronary artery disease being the most common cause. "In this population-based cohort, elevated GDF15 identified individuals with an adverse health profile, was independently associated with ischemic cardiomyopathy in men, and predicted mortality." (PMID 41977265, 2026). "Elevated GDF15 was independently associated with ischemic cardiomyopathy (OR 3.34, 95% CI: 1.38-8.11), particularly in men (OR 4.26, 95% CI: 1.40-12.96), but not in women." (PMID 41977265, 2026).
Kearns-Sayre syndrome (2 papers, 2021 to 2022). Kearns-Sayre syndrome (KSS) is a mitochondrial disease characterized by progressive external ophthalmoplegia (PEO), pigmentary retinitis and an onset before the age of 20 years. "GDF-15 levels were highest in participants with Kearns-Sayre Syndrome (KSS, n = 12), at 3,093 ± 545.4 pg/mL as compared to other mtDNA and nuclear genetic aetiologies (p < 0.001)." (PMID 35071983, 2021).
kidney cancer (2 papers, 2016 to 2023). Primary or metastatic malignant neoplasm involving the kidney. "Our results clearly showed that, while GDF15 is usually upregulated in most cancers, it is downregulated in kidney cancers, especially in ccRCC." (PMID 38082448, 2023).
lymphopenia (2 papers, 2021 to 2023). Reduction in the number of lymphocytes. "GDF-15 levels also correlated with interleukin-6, C-reactive protein, ferritin and D-dimer levels and with neutrophilia and lymphopenia." (PMID 34829345, 2021).
macrosomia (2 papers, 2025). "GDM is an important risk factor for macrosomia, which may explain why GDF15 can improve the predictive efficiency of common indicators for macrosomia in GDM." (PMID 39716461, 2025). "In addition, high serum GDF15 levels were associated with increased risks of preterm delivery in non-GDM and macrosomia in GDM." (PMID 39716461, 2025). "Further confirmation of the potential role of GDF-15 as a predictor of fetal growth in GDM might have important clinical implications, given the current lack of reliable predictive biochemical markers for fetal growth and macrosomia in GDM pregnancy." (PMID 40283592, 2025). "The area under the preterm delivery ROC curve was 0.784 in non-GDM and the area under the macrosomia ROC curve was 0.787 in GDM, supporting that serum GDF15 level in second trimester can improve the predictive efficiency of common indicators for preterm delivery in non-GDM and macrosomia in GDM." (PMID 39716461, 2025).
Membrane Glomerulonephritis (2 papers, 2020 to 2022). "Studies conducted from our hospital showed that GDF-15 is a predictor of the progression of membranous nephropathy and adverse outcomes in immunoglobulin A nephropathy." (PMID 35204349, 2022).
multiple system atrophy (2 papers, 2022 to 2023). Multiple system atrophy (MSA) is a neurodegenerative disorder characterized by autonomic failure (cardiovascular and/or urinary), parkinsonism, cerebellar impairment and corticospinal signs with a median survival of 6-9 years. "(2020) suggested that serum GDF15 levels may be a potential diagnostic biomarker for multiple system atrophy patients compared with healthy controls and PD patients." (PMID 35068064, 2022).
muscle disorder (2 papers, 2022 to 2023). "In this respect, our results appoint GDF15 consideration as an additional, more general marker for muscle disorders." (PMID 37891738, 2023). "In IMNM patients and the group of patients with hereditary muscle disorders, we found a moderate correlation of GDF15 serum levels with age at sampling." (PMID 37891738, 2023). "The mean circulating GDF15 levels were 326 ± 204 pg/mL for healthy controls, 831 ± 656 pg/mL for patients with hereditary muscle disorders and 1201 ± 1017 pg/mL for IIM patients." (PMID 37891738, 2023). "Although not specific for any individual muscle disorder, measuring GDF-15 levels in the blood is a convenient and informative asset to the clinic with potential intervention-changing capacities." (PMID 36361969, 2022).
Myocardial necrosis (2 papers, 2016 to 2017). Irreversible damage to heart tissue (myocardium) due to lack of oxygen after a heart attack (myocardial infarction). "Biomarkers of myocardial necrosis as well as GDF-15 levels (967.10 pg/mL vs. 692.15 pg/mL, p<0.001) were significantly higher in patients suffering an AMI compared to NCCP patients." (PMID 28771550, 2017). "Our study demonstrated the superior sensitivity and specificity of GDF-15 over cTnI and EuroSCOREII in the early detection of myocardial necrosis after OPCAB." (PMID 27311391, 2016).
myositis (2 papers, 2023 to 2025). "We propose adding circulating CXCL10 and GDF15 to the blood-based diagnostic toolkit for myositis as a valuable patient-friendly approach." (PMID 37891738, 2023). "Our results demonstrate significantly higher concentrations of GDF-15 in juvenile myositis patients, including JDM and PM, as compared with HCs, consistent with what has been observed in adult IBM." (PMID 38058222, 2025). "Our study found significant elevation of serum CXCL10 and GDF15 levels in myositis patients." (PMID 37891738, 2023). "We propose that circulating CXCL10 and GDF15 levels could be of aid to diagnose myositis." (PMID 37891738, 2023). "GDF-15 levels exhibited strong positive correlations with DASs, including the DAS total score, DAS skin score, DAS muscle score and Childhood Myositis Assessment Scale." (PMID 38058222, 2025).
nasopharyngeal carcinoma (2 papers, 2025). A carcinoma arising from the nasopharyngeal epithelium. "In contrast, GDF15 overexpression decreased the LT-induced ferroptosis in nasopharyngeal carcinoma cells." (PMID 40552277, 2025). "Thus, LT triggers ferroptosis in nasopharyngeal carcinoma cells via regulation of SOX4/GDF15 axis." (PMID 40552277, 2025). "Investigating the genetic profile in nasopharyngeal carcinoma (NPC), it was found that gp96 and GDF15 were markedly upregulated in radioresistant tumor cell subclones and that the knockdown of GDF15 resulted in the restoration of radiosensitivity in vitro." (PMID 40868185, 2025).
nephritis (2 papers, 2020 to 2021). Inflammation of renal tissue. "In the present study, we used GDF15-deficient mice to investigate the role of GDF15 in anti-GBM nephritis." (PMID 32977372, 2020). "We conclude that GDF15 is induced anti-GBM nephritis and that our protocol (7 + 14 days) of autologous anti-GBM nephritis is suitable to study the role of GDF15 in glomerular inflammation." (PMID 32977372, 2020). "Moreover, we demonstrate the protective effects for GDF15, as GDF15-deficient mice exhibited increased proteinuria with an aggravated crescent formation and mesangial expansion in anti-GBM nephritis." (PMID 32977372, 2020). "Furthermore, Gdf15-/- mice with anti-GBM nephritis exhibited a decreased number of WT1 positive podocytes in the glomeruli." (PMID 32977372, 2020). "Moreover, GDF15-deficient mice showed increased levels of the CXCR3 receptor in activated T cells and increased levels of proteinuria with aggravated crescent formation and mesangial expansion in anti-GBM nephritis." (PMID 34669736, 2021). "We first asked if we could detect increased levels of GDF15 in mice following anti-GBM nephritis." (PMID 32977372, 2020). "Based on these data, we assumed that GDF15 might play a protective role in anti-GBM nephritis." (PMID 32977372, 2020). "Our results now show that the cytokine GDF15 protects from kidney injury and inflammation in a mouse model of anti-GBM nephritis." (PMID 32977372, 2020). "Further, we investigated the impact of GDF15 on renal inflammation as one of the key determinants of glomerular damage and albuminuria in the early phase of anti-GBM nephritis." (PMID 32977372, 2020).
ovarian tumor (2 papers, 2015 to 2020). "We also showed that GDF15 can be detected in sera from ovarian tumor-bearing mice after cisplatin exposure." (PMID 33086658, 2020). "Furthermore, we elucidated the pleiotropic functions of GDF15 in chemoresistance in ovarian tumors by generating a shRNA-mediated knockdown of GDF15 in A2780cis cells." (PMID 25490861, 2015).
periodontal disease (2 papers, 2016 to 2021). "Overall, our data suggest a pro-inflammatory role for GDF15 in periodontal disease and demonstrate that GDF15 partially modulates the force-induced excessive inflammatory response of PdLF under these conditions." (PMID 34948405, 2021). "Blocking GDF15 signaling may provide a potential opportunity to limit the excessive inflammatory response in PdLF of orthodontic patients suffering from periodontal disease." (PMID 34948405, 2021). "Furthermore, the model presented may elucidate important CHD biomarkers which should be measured in patients with periodontal disease to more adequately screen for CHD risk, namely HOMA, TNF-α, CRP, IL-6, GDF-15, OPG, MPO and fibrinogen." (PMID 27846870, 2016).
retinal disease (2 papers, 2020). "There is only one previous study aiming to assess GDF-15 concentration in patients with retinal disease with an inflammatory component." (PMID 31936869, 2020). "Thus, large longitudinal studies are necessary to verify the usefulness of GDF-15 in prediction of retinal disease progression." (PMID 33239667, 2020).
rheumatic heart disease (2 papers, 2025 to 2026). An autoinflammatory condition following an infection with Group A Beta Hemolytic Streptococcus (GABHS), in which the heart is attacked by antibodies formed in reaction to a recent GABHS infection. "Moreover, in patients with AF and rheumatic heart disease, elevated GDF-15 levels correlated with increased atrial fibrosis, suggesting a potential role for GDF-15 in the structural remodeling of the atria that underlies AF development and persistence." (PMID 41590509, 2026).
sarcoidosis (2 papers, 2021 to 2022). Sarcoidosis is a multisystemic disorder of unknown cause characterized by the formation of immune granulomas in involved organs. "Moreover, some proteins in Class 1, including IL17RA, growth differentiation factor 15, FK506-binding protein 10, and PLAT, are associated with sarcoidosis pathogenesis." (PMID 35178414, 2022). "SARS-CoV2 ORF8 host targets belonging to the sarcoidosis gene panel (IL17RA, EMC1, PLD3, GDF15, FKBP10, ADAM9, and PLAT) highlight significant pathways related to sarcoidosis pathogenesis." (PMID 34440765, 2021).
sarcoma (2 papers, 2019 to 2024). A usually aggressive malignant neoplasm of the soft tissue or bone. "In sarcomas, GDF-15 expression is elevated in metastatic osteosarcoma, linked to reduced survival, and promotes cell migration through the TGF-β pathway." (PMID 39283723, 2024). "Very limited information is available with regard to GDF-15 expression in sarcomas." (PMID 39283723, 2024).
sleep disorder (2 papers, 2020 to 2026). A change from the patient's baseline sleeping pattern, in the hours slept and/or an alteration/dysfunction in the stages of sleep. "We found a significant difference in the circulating levels of FGF21 and HN, but not GDF15, between patients and age-matched women without sleep disorders, who were enrolled in a previous study conducted in our laboratory." (PMID 32420904, 2020).
spinal cord injury (2 papers, 2022). Penetrating and non-penetrating injuries to the spinal cord resulting from traumatic external forces (e.g., WOUNDS, GUNSHOT; WHIPLASH INJURIES; etc.). "Gdf15 is found in oligodendrocytes of the CC, and it is overexpressed in patients with stabilized MS, and also in functional recovery after traumatic spinal cord injury (SCI)." (PMID 36499195, 2022).
squamous cell carcinoma (2 papers, 2017 to 2023). A carcinoma arising from squamous epithelial cells. "Circulating GDF15 levels were significantly associated with increased age at diagnosis and the squamous cell carcinoma histology subtype." (PMID 37045997, 2023).
thrombotic disease (2 papers, 2023 to 2025). The formation of a blood clot in the lumen of a vessel or heart chamber; causes include coagulation disorders and vascular endothelial injury. "Thus, the GDF-15/GFRAL signaling pathway can possibly be considered a novel therapeutic target for thrombotic diseases." (PMID 38254638, 2023).